KPNA5 (karyopherin subunit alpha 5)
Description:
Functions in nuclear protein import as an adapter protein for nuclear receptor KPNB1. Binds specifically and directly to substrates containing either a simple or bipartite NLS motif. Docking of the importin/substrate complex to the nuclear pore complex (NPC) is mediated by KPNB1 through binding to nucleoporin FxFG repeats and the complex is subsequently translocated through the pore by an energy requiring, Ran-dependent mechanism. At the nucleoplasmic side of the NPC, Ran binds to importin-beta and the three components separate and importin-alpha and -beta are re-exported from the nucleus to the cytoplasm where GTP hydrolysis releases Ran from importin. The directionality of nuclear import is thought to be conferred by an asymmetric distribution of the GTP- and GDP-bound forms of Ran between the cytoplasm and nucleus. Mediates nuclear import of STAT1 homodimers and STAT1/STAT2 heterodimers by recognizing non-classical NLSs of STAT1 and STAT2 through ARM repeats 8-9. Recognizes influenza A virus nucleoprotein through ARM repeat 7-9 In vitro, mediates the nuclear import of human cytomegalovirus UL84 by recognizing a non-classical NLS.
Synonyms: SRP6; IPOA6
Tractability: PROTAC: ubiquitination databases record sites on it.
Gene: Protein-coding gene on chromosome 6 (116,681,187 to 116,741,867, forward strand). Ensembl gene ENSG00000196911.
Subcellular location: Cytoplasm
Subcellular location (Human Protein Atlas): Cytosol
Pathways (Reactome):
Disease: Maturation of DENV proteins; NS1 Mediated Effects on Host Pathways
Immune System: ISG15 antiviral mechanism
Gene Ontology:
Molecular function: protein binding; nuclear import signal receptor activity
Biological process: NLS-bearing protein import into nucleus; protein import into nucleus
Cellular component: cytosol; NLS-dependent protein nuclear import complex; nucleoplasm; cytoplasm
Genetic constraint (gnomAD): Loss-of-function variants: 22 observed, 34.95 expected, observed/expected ratio (o/e) 0.63, 90% interval 0.45 to 0.9. The upper end of that interval is the gene's LOEUF score, 0.9, which puts it in group 3 of 6, group 1 being the genes least tolerant of losing a copy. Missense variants: 361 observed, 401.42 expected, observed/expected ratio (o/e) 0.9, 90% interval 0.82 to 0.98. Synonymous variants: 141 observed, 137.98 expected, observed/expected ratio (o/e) 1.02, 90% interval 0.89 to 1.17.
Homologues: Orthologues: chimpanzee KPNA5 (99% identical), macaque KPNA5 (99% identical), dog KPNA5 (99% identical), rabbit KPNA5 (98% identical), pig KPNA5 (96% identical), rat Kpna5 (94% identical), guinea pig KPNA5 (94% identical), zebrafish kpna5 (89% identical), Drosophila melanogaster Kap-alpha1 (61% identical). Paralogues in human: KPNA6 (84% identical), KPNA1 (80% identical), KPNA2 (47% identical), KPNA4 (46% identical), KPNA3 (46% identical), KPNA7 (39% identical).
Diseases named in the same sentence as KPNA5 in open-access papers:
KPNA5 is named in the same sentence as 11 diseases in open-access papers, as found by Europe PMC text mining. Sharing a sentence is not in itself a finding about the gene and the disease. The quoted sentences say what the papers report.
Pancreatic Cancer (2 papers, 2023 to 2025). "Besides, a recent study indicates that KPNA5 is highly expressed in pancreatic cancer patients without gemcitabine resistance, and upregulation of KPNA5 increases the response of gemcitabine‐resistant PANC‐1 cells to gemcitabine." (PMID 40145330, 2025).
viral infection (2 papers, 2011 to 2021). "When analyzing gene expression in A549 cells, results showed a decrease in KPNA2 (p = 0.0285) and an increase in KPNA5 (p = 0.0266) upon viral infection." (PMID 34696514, 2021).
breast carcinoma (1 paper, 2015). "We found that overexpressed PHB2 interacted with KPNA1, KPNA5, and KPNA6, thereby leading to the E2-dependent translocation of PHB2 into the nuclei of breast cancer cells." (PMID 26052702, 2015). "In breast cancers, however, BIG3 captures PHB2 through its KPNA (KPNA1, KPNA5, and KPNA6)-binding region(s), thereby inhibiting the E2-dependent suppressive ability of PHB2." (PMID 26052702, 2015). "Here we report the mechanism by which BIG3 blocks the nuclear translocation of PHB2 via interactions with multiple karyopherin alpha (KPNA) proteins, including KPNA1, KPNA5, and KPNA6, in ERα-positive breast cancer cells." (PMID 26052702, 2015).
COVID-19 (1 paper, 2021). A disease caused by infection with severe acute respiratory syndrome coronavirus 2. "Results showed that COVID-19 patients had higher KPNA5 and lower KPNA7 expression compared with non-COVID-19 patients (p = 0.0025 and, p = 0.0017, respectively)." (PMID 34696514, 2021). "COVID-19 patients showed alterations in KPNA3, KPNA5, KPNA7, KPNB1, RHOA, and CDC42 expression compared with non-COVID-19 patients." (PMID 34696514, 2021).
lymph node metastasis (1 paper, 2025). "Additionally, low KPNA5 expression was significantly associated with advanced clinical stages and lymph node metastasis." (PMID 40145330, 2025). "Since the expression level of KPNA5 correlated with lymph node metastasis in patients, we further explored the effect of KPNA5 on the migration and invasive ability of ovarian cancer cells." (PMID 40145330, 2025).
ovarian carcinoma (1 paper, 2025). A malignant neoplasm originating from the surface ovarian epithelium. "In summary, our findings reveal for the first time that KPNA5 expression is downregulated in ovarian cancer and is associated with patients' poor prognosis." (PMID 40145330, 2025). "Low KPNA5 expression was associated with a poor prognosis in ovarian cancer patients." (PMID 40145330, 2025). "The expression level of KPNA5 in ovarian cancer tissues and cells was detected by IHC, Western blot, and qPCR." (PMID 40145330, 2025). "Note of worth, four genes (IPO9, KPNA2, TNPO3, and XPOT) and one gene (KPNA5) were consistently significantly up‐ and down‐regulated in ovarian cancer, respectively." (PMID 40145330, 2025). "In our study, we discovered that KPNA5 was abundantly expressed in normal ovarian tissues but significantly downregulated in ovarian cancer tissues." (PMID 40145330, 2025). "In this study, we found that PTPN4 is a key cargo protein of KPNA5 in ovarian cancer cells by mass spectrometry analysis of KPNA5‐bound proteins." (PMID 40145330, 2025). "The results showed that KPNA5 expression was lower in ovarian cancer tissues compared to adjacent normal tissues." (PMID 40145330, 2025). "To confirm the altered expression of KPNA5 in ovarian cancer, we examined the protein level of KPNA5 in ovarian cancer tissues using IHC staining." (PMID 40145330, 2025). "The silver staining results revealed a lot of proteins that bind with KPNA5 in ovarian cancer cells." (PMID 40145330, 2025). "Kaplan–Meier survival analysis revealed that ovarian cancer patients with low KPNA5 expression had shorter overall survival times." (PMID 40145330, 2025). "KPNA5 expression is downregulated in ovarian cancer (OC) tissues." (PMID 40145330, 2025). "Furthermore, exogenous overexpression of KPNA5 significantly inhibited the proliferation and invasion of ovarian cancer cells in vitro, as well as the growth of xenograft tumors in vivo." (PMID 40145330, 2025). "Moreover, overexpression of KPNA5 could significantly promote the transport of PTPN4 from cytoplasm to nucleus in ovarian cancer cells." (PMID 40145330, 2025). "The interaction between KPNA5 and PTPN4 was further confirmed by co‐IP and Western blot in ovarian cancer cells." (PMID 40145330, 2025).
prostate carcinoma (1 paper, 2017). A carcinoma that arises from epithelial cells of the prostate gland. "Indeed, deletion of the NLS sequence totally abolished the interaction between SPOP(WT, F125V, F133L) and overexpressed or endogenous KPNA5, suggesting that KPNA5 might participate in nuclear transport of wild-type and prostate cancer-associated SPOP mutants." (PMID 28448495, 2017).
infection (3 papers, 2011 to 2025). The state of being infected such as from the introduction of a foreign agent such as serum, vaccine, antigenic substance or organism. "Interestingly, KPNA5 appears upregulated upon infection, across the different datasets." (PMID 34696514, 2021). "Additionally, ferret infection with SARS-CoV-2 showed an increase in KPNA1, KPNA4, and KPNA5 expression (p = 0.0473, p = 0.0449, and p = 0.0371, respectively) when compared with the mock treatment." (PMID 34696514, 2021). "In addition, the expression levels of KPNB1, KPNA1, KPNA2, KPNA4, KPNA6, and KPNA7 changed with the infection time of the three strains while KPNA3 and KPNA5 did not change with the incubation time." (PMID 40687856, 2025).
tumor (3 papers, 2022 to 2025). "In this study, we found that KPNA5 expression is downregulated in OC through comprehensive analysis and explored its function as a tumor suppressor and underlying molecular regulatory mechanism." (PMID 40145330, 2025). "To further explore the underlying mechanism that KPNA5 exerts its tumor‐suppressive function, we identified the potential cargo proteins that bind with KPNA5 by using immunoprecipitation and mass spectrometry analysis (IP‐MS)." (PMID 40145330, 2025). "Overexpression of KPNA5 significantly suppressed OC cell proliferation, tumor growth, and invasion in both in vitro and in vivo studies." (PMID 40145330, 2025). "Our findings identify KPNA5 as a tumor suppressor in OC, presenting a potential therapeutic target for OC treatment." (PMID 40145330, 2025). "Moreover, the results of the subcutaneous xenograft model showed that overexpression of KPNA5 significantly repressed the tumor growth, and KPNA5 overexpressed SKOV3 cells derived tumors displayed lighter weights and lower Ki67 expression levels compared with control." (PMID 40145330, 2025). "However, it remains unclear which cargo proteins KPNA5 mediates into the nucleus to exert its tumor‐suppressive effects." (PMID 40145330, 2025).
cancer (2 papers, 2015 to 2023). A tumor composed of atypical neoplastic, often pleomorphic cells that invade other tissues. "In many cancers, KPNA5 is highly expressed and interacts with the tumor-suppressor gene PHB2." (PMID 37259332, 2023). "Due to limited research on KPNA5 in cancer, the expression and function of KPNA5 in PC have yet to be discovered; in particular, whether KPNA5 is related to GEM resistance is of particular interest to us." (PMID 37259332, 2023). "We validated the knockdown effect of each KPNA (KPNA1, KPNA5, and KPNA6) on the interactions between endogenous PHB2 and nuclear ERα in BIG3-depleted cancer cells." (PMID 26052702, 2015). "The results showed that the depletion of only BIG3 led to interactions between endogenous PHB2 released from BIG3 with nuclear ERα but that the depletion of BIG3 and KPNA1, KPNA5, and KPNA6 did not, indicating that PHB2 binding to nuclear ERα in cancer cells is KPNA-mediated." (PMID 26052702, 2015).
KPNA5 also shares sentences with these, for which no sentence is quoted: glioma (1 paper).